CYP27A1 (cytochrome P450 family 27 subfamily A member 1)
Diseases named in the same sentence as CYP27A1 in open-access papers (continued):
Sharing a sentence is not in itself a finding about the gene and the disease.
breast carcinoma (continued). "Conversely, we found a downregulation of VLDLR, whose genetic or epigenetic silencing contributes to gastric carcinogenesis, CYP27A1, which induces T cell dysfunction, thus promoting breast cancer progression and CCL2, downregulated in diffuse gastric cancer primarily in advanced stages." (PMID 34012923, 2021). "CYP27A1 protein expression is associated with higher breast tumor grade while the expression of CYP7B1 mRNA (a gene that encodes 7-α-hydroxylase) is associated with a better prognosis, indicating a clinically relevant role for 27-HC in breast cancer." (PMID 34571949, 2021). "Higher tumor CYP27A1 mRNA expression has been associated with better prognosis in women 50 or younger and with ERα-positive breast cancer, though other studies have not observed an association in a broader population." (PMID 32075687, 2020). "Importantly, atorvastatin was also found to decrease serum 27-HC and CYP27A1 expression in tumors of breast cancer patients." (PMID 31208017, 2019). "speculated that lowering circulating levels of 26-HC or inhibiting its synthesis by CYP27A1 may offer a strategy to prevent or treat breast cancer." (PMID 28087213, 2017). "Aggressive breast cancers were found to express high levels of CYP27A1, the enzyme converting cholesterol to 26-HC, indicating that 26-HC within tumours may contribute to the disease." (PMID 28087213, 2017). "High expression of the enzyme that catalyzes the conversion of cholesterol to 27HC, CYP27A1, is associated with higher tumor grade in breast cancers, and high expression of CYP7B1, the enzyme downstream of CYP27A1 is associated with better outcome in ER+ breast cancer patients." (PMID 26183823, 2015). "Cholesterol 27-hydroxylase (CYP27A1) and oxysterol 7-alpha-hydroxylase (CYP7B1) regulate 27HC concentrations, while differential expression of the liver X receptor (LXR) and estrogen receptor beta (ERβ) may impact the association between 27HC and breast cancer risk." (PMID 32075687, 2020). "Furthermore, the association between circulating 27HC and breast cancer risk may not vary by tumor expression of CYP27A1, CYP7B1, LXR-β, or ERβ." (PMID 32075687, 2020). "In human breast cancer tissue, 27-HC concentration was found to increase because of decreased catabolism, since CYP7B1 gene expression was downregulated, whereas CYP27A1 remained unchanged." (PMID 31208017, 2019). "Expression of CYP27A1, which converts cholesterol to 27-OHC is positively correlated to tumor grade in human breast cancer." (PMID 30283400, 2018). "27-HC, which is synthesized with CYP27A1 and released in an autocrine manner by myeloid cells, works on myeloid cells through LXR-ABCA1 to suppress cytotoxic CD8+ T cell activity, eventually promoting breast cancer progression." (PMID 39872079, 2022). "Similar prognostic potential of CYP27A1 and CYP7B1 in breast cancer has been reported." (PMID 27341022, 2016). "Another important cohort study reported the negative correlation between circulatory 27-HC levels and CYP27A1, ER, LXRs, and CYP7B1 expression levels in breast cancer." (PMID 38550382, 2024). "In this study, we found that the effects of LDL on cell proliferation were mediated by the activation of the cytochrome P450 enzyme, sterol 27 hydroxylase, and cholesterol 27-hydroxylase (CYP27A1) in both ER-α-positive and ER-α-negative breast cancer cells." (PMID 35011656, 2021). "Correlates of tumor protein expression of CYP27A1 and CYP7B1 with cancer characteristics, reproductive and lifestyle factors are not well established in cancer, including breast cancer." (PMID 32075687, 2020).
osteoporosis (18 papers, 2018 to 2026). A condition of reduced bone mass, with decreased cortical thickness and a decrease in the number and size of the trabeculae of cancellous bone (but normal chemical composition), resulting in increased fracture incidence. "Pharmacological interventions targeting this axis, such as the use of NPC1L1 inhibitors or Cyp27a1 antagonists, may provide novel strategies to prevent or treat bone loss associated with osteoporosis." (PMID 40496351, 2025). "Our findings establish the NPC1L1/C/EBPα/Cyp27a1/27‐OHC axis as a key mechanism underlying cholesterol‐mediated inhibition of osteogenesis and osteoporosis development." (PMID 40496351, 2025). "We also explored the role of NPC1L1 in osteoporosis (OP), focusing on the downstream C/EBPα/Cyp27a1/27‐hydroxycholesterol (27‐OHC) axis." (PMID 40496351, 2025).
atherosclerosis (17 papers, 2012 to 2024). A disease characterized by the build-up of fatty material and calcium deposition in the arterial wall resulting in partial or complete occlusion of the arterial lumen. "It is reported that mutations in CYP27A1 gene account for cerebrospinal xanthomatosis, a rare lipid storage disorder characterized by atherosclerosis and neurological progressive dysfunction." (PMID 38451044, 2024). "Taken together, these data suggest a protective role of normal CYP27A1 hydroxylation activity in the development of atherosclerosis and the consequent CVD risk." (PMID 29951035, 2018). "To test the effect of CYP27A1 deficiency on the development of atherosclerosis, we previously crossed Cyp27a1 knockout (KO) mice with Apolipoprotein E (ApoE) KO mice, and fed the offspring with a Western diet (WD) for 3 and 6 months." (PMID 29191818, 2018). "Knockout of Cyp27A1 in apolipoprotein E-deficient mice revealed a gene dose effect with a 10-fold reduction in atherosclerosis severity observed in double knockout mice, and Cyp27A1 heterozygosity leads to accelerated atherosclerosis." (PMID 30283400, 2018). "The present investigation was initiated with studies determining how atherosclerosis is impacted by macrophage sterol 27-hydroxylase (cyp27a1), which catalyzes cholesterol conversion to 27-hydroxycholesterol (27HC) and cholestenoic acid." (PMID 37491347, 2023). "A previous experiment showed that by regulating cholesterol efflux and macrophage polarization through elevated CYP27A1 activation, vitamin D played a protective role against atherosclerosis in hypercholesterolemic swine." (PMID 34745384, 2021). "In our previous study, Cyp27a1 deficient mice on ApoE−/− background, (DKO mice), fed with WD developed 10-fold less atherosclerosis than their ApoE KO littermates." (PMID 33193099, 2020). "The effect of RIF on development of atherosclerosis was less pronounced in het mice with reduced Cyp27a1 expression." (PMID 29191818, 2018). "In conclusion, despite a similar induction level of Cyp3a11 expression in the liver, RIF had a different effect on plasma lipids and atherosclerosis development in young ApoE KO and het mice, revealing the importance of Cyp27a1 gene dosage in vivo in mice." (PMID 29191818, 2018). "Further studies, such as knocking down Cyp3a11 in ApoE KO and het mice would largely contribute to the clarification of the role of Cyp27a1 and Cyp3a11 in atherosclerosis development." (PMID 29191818, 2018). "In contrary, het mice with reduced Cyp27a1 expression had much more atherosclerosis than ApoE KO mice." (PMID 29191818, 2018). "Based on our observations in DKO mice and to investigate the relevance of CYP3A11 for cholesterol homeostasis, we analyzed the effect of Cyp3a11 induction by RIF on atherosclerosis in ApoE KO and het mice with reduced Cyp27a1 expression." (PMID 29191818, 2018). "Our proposed mechanism on the beneficial effects of increased hepatic CAV‐1 on protection against atherosclerosis in DKO mice remains to be verified in humans with reduced CYP27A1 activity." (PMID 28149711, 2016). "CYP27A1 has therefore many implications to the development of atherosclerosis and cardiovascular disease." (PMID 26480823, 2015). "With regards to the alternative pathway of bile acid synthesis, the regulation of CYP27A1 is relevant mainly for cholesterol reverse transport and protective mechanisms against atherosclerosis." (PMID 22343367, 2012). "We now reveal that in macrophages, which are the primary plaque immune cell expressing cyp27a1, the enzyme promotes atherosclerosis by coupling hypercholesterolemia to endothelial activation and vascular inflammation, being responsible for the majority of macrophage accumulation in the artery wall." (PMID 37491347, 2023). "In addition, in mice in which effects of gene dosage are readily evaluated, homozygous versus heterozygous global deletion of cyp27a1 has yielded opposing effects on atherosclerosis severity." (PMID 37491347, 2023).
atherosclerosis (continued). "Thus, mice and humans have a similar profile for cyp27a1 transcript abundance in immune cells relevant to atherosclerosis pathogenesis, with expression primarily demonstrable in macrophages." (PMID 37491347, 2023). "However, homozygous versus heterozygous global deletion of cyp27a1 in mice yields opposing effects on atherosclerosis severity." (PMID 37491347, 2023). "Seeking to delineate how macrophage cyp27a1 influences atherosclerosis, in the present project the initial hypothesis raised was that macrophage cyp27a1 affords atheroprotection." (PMID 37491347, 2023). "Based on these findings, we conclude that, first, the differences in the effect of RIF on development of atherosclerosis was mainly due to the level of Cyp27a1 expression in the liver and, second, that RIF treatment was less effective when Cyp27a1 expression was reduced." (PMID 29191818, 2018). "The atherosclerosis observed in ApoE KO was abolished in Cyp27a1/ApoE double knockout (DKO) mice." (PMID 28149711, 2016). "Evaluations of atherosclerotic lesion size demonstrated that relative to mice deficient in both macrophage cyp27a1 and endothelial septin 11, the provision of either the endothelial septin 11 protein or the macrophage enzyme alone did not advance atherosclerosis." (PMID 37491347, 2023). "Conversely, we observed a higher CYP27A1 expression in AMI compared to stable CAD, implying sterol‐27 hydroxylase acts as protective factor against atherosclerosis." (PMID 38451044, 2024). "Of all candidate genes for Ath30, Crygc and Mogat1showed a negative correlation with atherosclerosis in their hepatic transcript levels, Cyp27a1 showed a negative and Acsl3 a positive correlation with atherosclerosis in aortic transcript levels." (PMID 33109727, 2020). "Favorable changes in lipid profile consisting in a decrease in plasma TC and LDL-C combined with an increased in plasma level of HDL-C and increased CYP27A1 activity, is a likely reason for which ApoE KO mice treated with RIF developed less atherosclerosis than their vehicle-treated littermates." (PMID 29191818, 2018). "Cyp27a1(−/−)/Apolipoprotein E(−/−) double knockout mice (DKO) fed a western diet failed to develop atherosclerosis." (PMID 28149711, 2016). "In cultured cells CYP27A1 was found to be transcriptionally up-regulated by some nuclear receptors, such as retinoid X receptor (RXR) and PPAR gamma, thus suggesting a possible protective role of these receptors against atherosclerosis." (PMID 22343367, 2012).
prostate carcinoma (16 papers, 2013 to 2025). A carcinoma that arises from epithelial cells of the prostate gland. "Studies demonstrated that CYP27A1 deficiency increased the proliferative activity of melanoma cells and prostate cancer cells." (PMID 36872411, 2023). "CYP27A1 has been identified as a potential biomarker, and decreased expression of CYP27A1 has been linked to a worse prognosis in prostate cancer." (PMID 37817081, 2023). "Loss of CYP27A1 has been determined to dysregulate cholesterol homeostasis in prostate cancer; the same was found for the gene ABCA1." (PMID 35453307, 2022). "Variation of SNPs on VDR and CYP27A1 was associated with lethal prostate cancer even after adjustment for 25(OH)D levels." (PMID 30249031, 2018). "The results of this study showed that CYP27A1 is significantly downregulated in bladder cancer tissues, and its expression level is negatively correlated with disease risk, which is consistent with the findings reported in prostate cancer." (PMID 40755754, 2025). "Studies have shown that CYP27A1 is downregulated in prostate cancer tissues, and restoration of its expression inhibits prostate cancer cell growth by increasing 27-HC production." (PMID 40755754, 2025). "We previously reported that cholesterol homeostasis in prostate cancer (PC) is regulated by 27-hydroxycholesterol (27HC) and that CYP27A1, the enzyme that converts cholesterol to 27HC, is frequently lost in PCs." (PMID 38188290, 2023). "Silencing the expression of the CYP27A1 gene can slow down the growth rate of prostate cancer cells in vitro and transplanted tumors." (PMID 35692496, 2022). "Furthermore, as one of the vitamin D pathway genes, CYP27A1 has some impact on prostate cancer chemoprevention based on vitamin D metabolism and has the ability to predict the prognosis of prostate cancer patients." (PMID 36936948, 2023). "Besides, the expression of CYP27A1 was found to be related to the proliferation of tumor cells, including those in colon, breast, and prostate cancer." (PMID 37817081, 2023). "We constructed ceRNA networks in the prostate cancer microenvironment and identified lncRNA LINC01082, miRNA hsa-miR-133a-3p, and genes TTLL12, PTGDS, GAS6, CYP27A1, PKP3, and ZG16B as the potential biomarkers to predict prognosis for prostate cancer." (PMID 35075375, 2022). "lncRNA LINC01082, miRNA hsa-miR-133a-3p, and genes TTLL12, PTGDS, GAS6, CYP27A1, PKP3, and ZG16B are the top RNAs having the potential to predict prognosis for prostate cancer." (PMID 35075375, 2022). "The most interesting 8 prognostic biomarkers for prostate cancer included lncRNA LINC01082, miRNA hsa-miR-133a-3p, and genes TTLL12, PTGDS, GAS6, CYP27A1, PKP3, and ZG16B." (PMID 35075375, 2022). "Finally, survival analysis, biological function analysis, and literature researched identified 8 key biomarkers (lncRNA LINC01082, miRNA hsa-miR-133a-3p, mRNA TTLL12, PTGDS, GAS6, CYP27A1, PKP3, and ZG16B) to predict prostate cancer prognosis." (PMID 35075375, 2022). "Interestingly, the CYP27A1 expression level is inversely correlated to prostate cancer development and progression, while the CYP7B1 enzyme level is significantly upregulated during prostate cancer prognosis, suggesting that 27HC might be actually beneficial against prostate cancer." (PMID 32650428, 2020).
melanoma (10 papers, 2011 to 2024). A malignant, usually aggressive tumor composed of atypical, neoplastic melanocytes. "Only CYP27A1, encoding 27-hydroxylase, which catalyzes the conversion of cholesterol to 27HC, was highly expressed in melanoma patients compared to normal patients and melanocytes according to the TCGA-SKCM cohorts." (PMID 38775844, 2024). "Accordingly, forced expression of CYP27A1 only in melanoma cells increased cellular 27HC content, caused vemurafenib resistance, and promoted melanoma spheroid propagation in both A375 and A2058 melanoma cells, independent of DHCR24 induction." (PMID 38775844, 2024). "We also found that DHCR24 strongly upregulated the expression of CYP27A1 in melanoma cells, indicating a positive feedback loop leading to cellular accumulation of 27HC." (PMID 38775844, 2024). "Dafadine-A, a CYP27A1 inhibitor, attenuates cholesterol-induced growth of melanoma spheroids and abrogates the resistance property of vemurafenib-resistant melanoma cells." (PMID 38775844, 2024). "Next, we sought to determine the effect of dafadine-A, a novel inhibitor of DAF-9 cytochrome P450 in the nematode Caenorhabditis elegans and the mammalian ortholog of DAF-9 (CYP27A1), on melanoma cells." (PMID 38775844, 2024). "Exploiting the expression of melanogenesis-associated transcription factor target gene CYP27A1 and inhibiting mitochondrial OxPhos suggest a strategy for BRAF/NRAS mutant melanoma." (PMID 35311151, 2022). "CYP11A1 is also expressed in normal melanocytes and melanoma cells, so these cells can potentially carry out the CYP11A1-initiated pathways of vitamin D metabolism, with subsequent modification of products by CYP27B1, CYP24A1, or CYP27A1, which are also expressed in melanoma cells." (PMID 38927967, 2024). "Accordingly, CYP27A1 is highly expressed in melanoma patients and upregulated by DHCR24 induction." (PMID 38775844, 2024). "Finally, we confirmed that the effects of cholesterol on melanoma resistance require its metabolite 27HC through CYP27A1 catalysis, and that 27HC further upregulates Rap1A/Rap1B expression and increases AKT phosphorylation." (PMID 38775844, 2024). "At the same time, our data show that DHCR24 induces CYP27A1 expression and increases HMGCR and CYP27A1 expression in vemurafenib-resistant melanoma cell lines, suggesting an enhanced regulatory loop mechanism." (PMID 38775844, 2024). "CYP27A1 and CYP27B1 are expressed in MeWo, SK-Mel28, SM, SK-Mel-5, SK-Mel-25, IGR, and MelJuso melanoma cell lines; however, the last four cell lines in this list are not responsive to 25(OH)D3 and calcitriol treatment." (PMID 38672780, 2024). "Our western blot analysis confirmed increased expression of CYP27A1, which was upregulated in the bile acid metabolic pathway, and three additional glycolytic genes (PKM2, PHGDH, and PCK2) in melanoma CD8+ TILs compared to PBMCs." (PMID 38023136, 2023). "CYP27A1, a key regulatory enzyme of the bile acid metabolism pathway, was significantly upregulated in the CD8+ T cells of melanoma TILs as compared to PBMCs." (PMID 38023136, 2023). "CYP27A1, CYP27B1, and CYP2R1 are involved in the activation of vitamin D, whereas CYP24A1 and CYP3A4 are responsible for the degradation of the active vitamin D. CYP24A1, the primary catabolic enzyme of calcitriol, is overexpressed in melanoma tissues and cells." (PMID 38672780, 2024). "PCR fragments characteristic for VDR, CYP27A1 and CYP27B1 mRNAs were below the level of detectability in SK-MEL-188b melanoma, which did not respond to vitamin D. Only the mRNA of PDIA3 was detected in this line." (PMID 30200275, 2018).
breast tumor (9 papers, 2013 to 2023). "The significant associations between high intratumoral levels of CYP27A1 with aggressive breast tumor biological features seen in this study are consistent with previous reports and align with the preclinical evidence supporting a pathogenic role of the 27HC/CYP27A1 metabolic pathway in BC." (PMID 33176848, 2020). "Differential expression of CYP27A1 has been observed in breast tumours correlating with the phenotype and prognosis of the disease." (PMID 33809117, 2021). "Inhibition of CYP27A1 with aromatase inhibitors, such anastrozole and fradrozole, has also proved to be beneficial in treating breast tumours dependent on ER signaling." (PMID 33809117, 2021). "However, one study suggests similar expression of CYP27A1 but markedly different CYP7B1 in normal vs. breast tumor tissue." (PMID 32075687, 2020). "The Cancer Genome Atlas data analysis showed that CYP27A1 levels are more or less similar in breast tumours and normal breast tissues, whereas the CYP7B1 expression is significantly lower in breast tumours." (PMID 37614064, 2023). "However, cytochrome P450 family 27 subfamily A member 1 (CYP27A1), a cytochrome p450 oxidase needed for the transformation of cholesterol to 27-hydroxycholesterol (27HC), is highly expressed on macrophages infiltrated in the breast tumor." (PMID 34742349, 2021).
Lipid storage disease (9 papers, 2014 to 2024). "CYP27A1 is another crucial gene that has a role in bile acid metabolism, cholesterol metabolism, steroid synthesis, and lipid biosynthesis, further emphasising its relevance in regulating cholesterol levels and preventing rare lipid storage diseases." (PMID 39457550, 2024).